KRAS (KRas proto-oncogene, GTPase)
Diseases named in the same sentence as KRAS in open-access papers (continued):
Sharing a sentence is not in itself a finding about the gene and the disease.
cancer (continued). "VDR expression rates were associated with KRAS mutation in several cancer types." (PMID 23691496, 2013). "KRAS is involved in several signalling pathways and mutations in this gene may lead to cancer development." (PMID 23384026, 2013). "Moreover, they are highly associated with cancer metastasis and the expression of oncogenic factors (KRAS, MYC and MDR1)." (PMID 23069990, 2013). "While there is some evidence that KRAS exon 2 mutations may be associated with a worse prognosis, and that G13 mutations may result in a less aggressive cancer, the evidence regarding the different effects of specific G12 or G13 variants is sparse." (PMID 24066160, 2013). "The prevalence of KRAS mutations in a variety of cancers underscores the promise that targeting KRAS may have in treating cancer." (PMID 23202889, 2012). "Our results also indicate that direct sequencing is only of limited utility when trying to detect mutations in the KRAS gene in cancer tissues, since this method only detected KRAS mutations in 6 of the 131 DNA samples tested, even though 21 were found to contain mutations by other methods." (PMID 22995035, 2012). "Since KRAS is frequently mutated in human cancer, many cancers will have constitutive mTOR activity, but may not be sensitive to rapamycin as they will have Raf/MEK/ERK pathway activation." (PMID 23085539, 2012). "In the BRAFwt/MSS cohort, a KRAS mutation was present in 41/90 (46%) cancers." (PMID 23110075, 2012). "Slack and Weidhaas hypothesize that patients with lung tumors containing activating KRAS mutations would also be ideal candidates for such a therapy; exogenous let-7 would add another block to the development of the cancer." (PMID 22191027, 2012). "Given the increasing literature on a critical role of the KRAS variant in human cancers, more studies are needed to unravel the functional role of the KRAS variant and delineate the exact mechanism of the putative cross-talk between the KRAS variant and steroid hormone exposure." (PMID 22436609, 2012). "Mutations in the KRAS oncogene are often found in human cancers." (PMID 22995035, 2012). "Although a common mutation in cancer, KRAS has been difficult to therapeutically target." (PMID 23202889, 2012). "KRAS mutations and their implications in cancer development have been studied for over 40 years." (PMID 23202889, 2012). "The BRAFwt/MSS cancers had a 46% (41 of 90) KRAS mutation rate." (PMID 23110075, 2012). "Of the three known human RAS genes, KRAS is most frequently mutated in cancer." (PMID 23202889, 2012). "At present, the amount of cancer cells in the biopsy should at least be sufficient for an analysis of the KRAS mutational status, since treatment with an epithelial growth factor receptor (EGFR) inhibitor could be an option in the future." (PMID 22512246, 2012). "However, cancers harboring KRAS mutations are likely to be insensitive to single-agent PI3K inhibitors and showed synergism in combination treatment with MEK inhibitors." (PMID 22159814, 2012). "20-25% all human cancers, KRAS mutations account for about 85%, NRAS for about 15%, HRAS for <1%." (PMID 21422497, 2011). "As a prognostic marker, PIK3CA mutations are associated with shorter cancer-specific survival, but this effect may be limited to patients with KRas wild-type tumors." (PMID 21403829, 2011). "Mutation or activation of KRAS results in constitutive activation of several downstream effectors, and to date it has not been clear which effectors are most important in mediating the effects of mutated KRAS in cancer cells." (PMID 21910869, 2011). "Our data suggest that agents inhibiting both HIF-1α and HIF-2α, or their target genes, may likely be effective in treating cancers with oncogenic KRAS mutations." (PMID 21073737, 2010). "Similarly other markers such as KRAS had been suggested as prognostic markers, but KRAS mutations have been observed in several cancers and its importance as prognostic marker is still controversial." (PMID 21170319, 2010).
cancer (continued). "Therefore, knowledge of the KRAS gene mutation status is essential before the decision is made to treat a cancer patient using EGFR-targeted Panitumumab and Cetuximab therapy." (PMID 21197450, 2010). "However, cancers with oncogenic KRAS mutations are primarily resistant, due to persistent signaling through these pathways." (PMID 21073737, 2010). "Cancer cell lines harboring KRAS mutations could be broadly divided into KRAS-dependent and KRAS-independent groups." (PMID 19826477, 2009). "In contrast in KRAS mutant cancers, a concurrent LKB1 mutation may be required to enhance mTOR activation." (PMID 18594528, 2008). "Cancer cell lines with known KRAS mutations were first used to test the HRM methodology." (PMID 17184525, 2006). "Thus, we hypothesised that cancers harbouring dual KRAS mutation/STK11 inactivation might be particularly vulnerable to targetting mTOR signalling." (PMID 40069402, 2025). "The integration of multidimensional datasets by combining machine learning and bioinformatics approaches could provide deeper insights into the intricate KRAS‐related networks underlying cancer progression and unveil novel biomarkers and potential therapeutic targets." (PMID 40013338, 2025). "Finally, we discuss emerging strategies on the horizon, including better patient selection and novel drug combinations, that hold promise for overcoming existing limitations and advancing the field toward more effective and durable therapeutic solutions for patients with KRAS G12C-mutated cancers." (PMID 40940900, 2025). "If a SAM-like or PSAR cell that has inherited the part of chromosome 12 with mutated KRAS were to invade or merge with a distant cell in a different tissue, the incorporation of the cancer-promoting gene could, theoretically, destabilize that cell or tissue and cause a secondary carcinoma." (PMID 41446211, 2025). "Moreover, we postulate that the degree of the cancer-promoting impact of NAT10 in CRC might be related to the mutation status of KRAS." (PMID 39905540, 2025). "In addition, the G12D and G12V mutations were associated with poor therapeutic outcomes in BTC patients who received GCD therapy, suggesting that KRAS variants may predict reduced efficacy of cancer immunotherapy regimens, including ICIs." (PMID 40499463, 2025). "For example, the predicted sensitivity to mTOR inhibitors in the high-risk group contrasts with some preclinical evidence suggesting that KRAS-driven cancers, potentially relevant to pathways enriched in our high-risk group, might exhibit resistance to PI3K/mTOR pathway inhibition." (PMID 40607411, 2025). "Therefore, while KRAS mutations can be present in both types of cancers, they may be more prevalent in CRC development." (PMID 40447784, 2025). "Additionally, emerging perspectives suggest a possible involvement of local neurogenesis and somatic cancer-driving mutations (KRAS), which could offer promising avenues for future therapeutic interventions." (PMID 40157065, 2025). "However, while MEK inhibitors have shown clinical efficacy in several types of KRAS-mutated cancers, preclinical studies in CRC revealed that treatment with MEK inhibitor alone was not very effective in KRAS-mutated CRC cells due to different mechanisms of acquired resistance." (PMID 40076613, 2025). "Macropinocytosis could also play a role in targeting KRAS-mutated cancers and has shown mechanistic differences in macropinocytosis in allele KRAS G12R, where impaired activation of the effector p110alpha PI3K occurs, exposing potential therapeutic vulnerabilities." (PMID 40805153, 2025). "Besides, HLA-peptide prediction algorithms have revealed that HLA-A*11:01 may bind peptides harboring KRAS mutations in patients with various common cancer types." (PMID 41184283, 2025). "Therefore, the CBL and MAPK3 changes observed in this study may reflect a rebalancing of EGFR signaling that can lead to inhibition of cancer cell growth, even in the presence of KRAS mutations." (PMID 41226554, 2025).
cancer (continued). "Furthermore, given that PAKs are downstream players of RAS, this may also partially explain the effect of KRAS mutation on downregulating cancer cell surface MHC I." (PMID 39941877, 2025). "KRAS signaling in acinar cells and inflammatory pathways in immune cells could act as upstream factors activating and supporting (trans-) differentiation into cancer-associated fibroblasts in a paracrine manner." (PMID 39811640, 2025). "Finally, our study did not account for other potential confounding factors that could influence VAT and cancer outcomes, such as KRAS mutations and lifestyle factors." (PMID 40170387, 2025). "In addition to their biochemical properties, KRAS G12C cancers present a distinct co-mutation pattern that may influence the response to selective inhibitors and other treatments." (PMID 40940900, 2025). "Also, mutations in the KRAS gene enhance cancer cell adaptation to metabolic stress." (PMID 40429703, 2025). "Similarly to IL-6, the CXCR2 (C-X-C motif chemokine receptor 2)/IL-8 axis induced by KRAS was shown to be crucial for promoting phenotype alterations of CAFs (cancer-associated fibroblasts) and increased secretion of pro-tumoral cytokines that eventually promoted the development of PDAC." (PMID 40427186, 2025). "Furthermore, we found that cancer cells exhibited dominant expression of the mutated alleles, including those in the proto-oncogene KRAS (e.g., c.35G>T in CRC07, c.436G>A in HTCRC01 and c.38G>A in HTCRC05), KLF5 (c.935C>T in CRC07) and PIK3CA (c.2836G>T in CRC09)." (PMID 40702779, 2025). "Additionally, mutations along the KRAS pathway may be important for cancers of gallbladder and biliary tree." (PMID 40720480, 2025). "These reasons could potentially explain why KRAS mutations occur so frequently in cancers." (PMID 40002297, 2025). "Within the 50 cancer hallmarks, the PyroScore showed the strongest positive correlation with DNA repair, reactive oxygen species and the G2M checkpoint, while it was negatively associated with Hedgehog signaling, UV_Response_DN and KRAS signaling (all P < 0.001)." (PMID 38287330, 2024). "Moreover, KRAS is mutated at position 12 (G12X) in ~80% of RAS-driven cancers." (PMID 38473778, 2024). "Notably, the copy numbers of cancer-associated genes such as KRAS, ETV1, and SMAD2, displayed a subtype-specific increase in prevalence and magnitude along PDAC progression, highlighting the importance of matched primary and metastatic samples for uncovering such patterns." (PMID 38702773, 2024). "Moreover, cancer cells with KRAS mutations appear to be more dependent on NPM1 expression." (PMID 38275900, 2024). "Furthermore, the frequency of KRAS mutations in various cancer types is very different." (PMID 38473821, 2024). "While G4s have been predominantly associated with the promoters of oncogenes such as MYC, KIT or KRAS, where their stabilization is associated with suppressed oncogene expression, we explored their potential role in exonic regions and the associated impact on genomic instability in cancer patients." (PMID 38407356, 2024). "Not only specific KRAS mutations could influence the pathological nature of cancer or its therapeutic response, but also the co-occurrence and correlation of other driver mutations with KRAS could significantly influence OS, PFS, or disease recurrence and therapeutic management." (PMID 39056802, 2024). "Furthermore, despite thorough sequencing studies, no significant point mutations, whether germline or somatic, were identified in frequently mutated cancer-associated genes such as KRAS, BRAF, and PIK3CA, concerning SFT." (PMID 39364485, 2024).
cancer (continued). "Analysis of CRISPR–Cas9 functional genetic screening data demonstrated that KRAS-mutated cancer cell lines are highly sensitive to disruption of the KRAS locus, and KRAS mutation status was the only genetic feature that exhibited a significant correlation with KRAS dependency." (PMID 38589574, 2024). "The causes and purposes of isoform-specific alterations in KRAS transcriptional abundance during the transition to cancer are currently unknown, underscoring the distinct but only partially understood roles played by KRAS4a and KRAS4b in specific physiological contexts." (PMID 38354232, 2024). "Interestingly, the DTP-DTEP transition was associated also with downregulation of several cancer hallmark gene sets, most apparently seen in set 4 where KRAS signaling, EMT, WNT/ß-catenin, and inflammatory response genes were all suppressed upon proliferation reactivation." (PMID 38886591, 2024). "However, the metabolic phenotype of KRAS-mutated cancer cells is also influenced by the TME." (PMID 39164274, 2024). "This may explain the rarity of STAT3 GOF mutations in human cancers with mutant KRAS." (PMID 38573819, 2024). "This response disparity between CRC and other KRAS-mutant cancer types to allele-specific inhibitors of KRASG12C and KRASG12D raises the possibility that tissue-specific molecular events may underlie the mechanism of limited efficacy, which has not yet been clearly defined." (PMID 37020035, 2023). "Mechanistically, the TME affects cancer cells through complex and dynamic pathways to modulate cancer-associated signaling, involving ligand-receptor interactions (e.g., PD-L1 binding of cancer cells to PD-1 of T cells), cytokines, metabolism reprogramming and KRAS pathways." (PMID 37187730, 2023). "In addition, LKB1 and KEAP1/NRF2 pathways synergistically promote metabolic reprogramming toward enhanced glutamine dependence in lung adenocarcinoma with mutated KRAS, and they also enhance the sensitivity of cancer cells to CB-839 (GLS inhibitor) in vitro and in vivo." (PMID 36959802, 2023). "Finally, new hope for solid tumor patients comes from a compound that probably represents the first idea of a small molecule cancer cell inhibitor since it targets one of the most common, and even for years considered undruggable, mutated protein in cancers, KRAS G12C." (PMID 37627201, 2023). "In the case of KRAS, different mutant phenotypes may have different prognosis and thus different treatment modalities, and activating mutations and deletions can also express different cancer-driven capabilities." (PMID 37360159, 2023). "Kirsten rat sarcoma viral oncogene homolog (KRAS) is an oncogene frequently mutated in various types of cancer; the protein was considered undruggable until the crystal structure of the G12C mutant was solved, revealing a previously unknown pocket suitable for small molecule binding." (PMID 38202651, 2023). "Therefore, targeting KRAS mutations is regarded as the “holy grail” of targeted cancer therapies." (PMID 37110848, 2023). "Furthermore, clinical evaluation supported their approval (May–June 2021) by the FDA for the treatment of NSCLC cancer patients with the KRAS G12C mutation." (PMID 37111737, 2023). "However, most studies did not evaluate these mutations exclusively (e.g., patients with a KRAS‐mutant or KRAS wild‐type cancer may have had another mutation in a different gene), which could have potentially diluted their results." (PMID 35785488, 2023). "KRAS mutations are context specific, and a mutation may act differently in different cancer types." (PMID 36808143, 2023). "Indeed, cancer-free mice may have a high level of KRAS mutation, but this is neutralized by a high level of let-7a expression." (PMID 37511536, 2023).
cancer (continued). "We finally conclude that these four bioflavonoids have potential inhibitory activity against the KRAS G12D mutant, and are further to be studied in vitro and in vivo, to evaluate their therapeutic potential and the utility of these compounds against KRAS G12D mutated cancers." (PMID 36975507, 2023). "Therefore, combination therapy of KRAS pathway inhibitors and autophagy inhibitors could represent a new strategy to treat KRAS-mutated cancers." (PMID 37996408, 2023). "Therefore, the metabolic importance of metformin may be of special interest in cells with KRAS mutations, as this driver alteration is metabolically involved in cancer progression." (PMID 36901764, 2023). "However, discovering drugs that could benefit patients with cancer whose tumors harbor KRAS G12D and KRAS G12V mutations remains a significant unmet need, because the prevalence in human cancers of these mutations is higher than that of KRAS G12C mutations." (PMID 38051103, 2023). "Thus, SSA with BRAF mutations and TA/TVA with KRAS mutations may have a selective advantage for progressing to carcinoma when their TSGs are hypermethylated and inactivated through Fn infection." (PMID 37772997, 2023). "Thus, these potential pathways which are all recognized as the cancer-related pathways could be described in the context of the KRAS mutation." (PMID 35562390, 2022). "Given the remarkable therapeutic efficacy we observed with the TRAIL–CDK9i combination in various models of hard-to-treat cancers, one may envisage that this treatment combination may become widely applicable in cancer therapy, including in the treatment of KRAS-mutated cancers." (PMID 34535764, 2022). "Most studies have concluded that there is a negative influence on prognosis of patients with a KRAS mutation whether or not they have undergone surgery for other solid tumors and a correlation between oncogenic KRAS mutations and PD-L1 expression in cancers has also been emphasized." (PMID 35305624, 2022). "Considering the high incidence of KRAS mutations and the poor prognosis associated with them, it is urgent to find new approaches for the treatment of cancers harboring KRAS mutations, and elucidating KRAS mutations involvement in apoptosis/autophagy regulation may contribute to such an aim." (PMID 35883626, 2022). "Thus, these mutations may play a role in resistance of a subset of BRAF mutated cancers to targeted therapies, through the extensive crosstalk of the KRAS/RAF/MEK/ERK and the PI3K/AKT/mTOR pathways." (PMID 36079062, 2022). "The frequency of KRAS variation in our cohort was 12.4%, which is higher than in The Cancer Genome Atlas and Memorial Sloan Kettering Integrated Mutation Profiling of Actionable Cancer Targets cohorts (3.3% and 6.3%, respectively), possibly due to differences in racial or etiological factors." (PMID 34730772, 2022). "Therefore, the signaling pathways attributed to the DEGs under study are mainly involved in cancer and may provide new insights for understanding the cellular events underlying KRAS tumorigenesis." (PMID 35562390, 2022). "Thus, upregulating DUSP6 or other phosphatases may allow cancer cells to harbor amplification of mutant KRAS alleles." (PMID 36418460, 2022). "But in what may turn out to be one of your most-impactful identifications, you developed the first covalent inhibitor of KRAS [the most commonly mutated oncogene, associated with poor responses to standard cancer therapies], specifically with the G12C mutation." (PMID 35234864, 2022). "It was also reported that cancer cells with KRAS mutations could recruit myeloid-derived suppressor cells to secrete granulocyte–macrophage colony-stimulating factor, effectively limiting the infiltration level and decreasing the antitumor activities of CD8+ cytotoxic T-cells." (PMID 35571489, 2022).